PDF (peptide deformylase, mitochondrial)
Description:
Removes the formyl group from the N-terminal Met of newly synthesized proteins.
Tractability: Small molecule: a structure with a bound ligand is known; a high-quality ligand is known; it has a binding pocket of medium quality; it belongs to a druggable protein family. PROTAC: its protein half-life has been measured; a small molecule that binds it is known.
Target class: Enzyme; Hydrolase
Gene: Protein-coding gene on chromosome 16 (69,326,913 to 69,330,588, reverse strand). Ensembl gene ENSG00000258429.
Subcellular location: Mitochondrion
Subcellular location (Human Protein Atlas): Mitochondria; Nucleoplasm
Gene Ontology:
Molecular function: peptide deformylase activity
Biological process: peptidyl-methionine modification; positive regulation of cell population proliferation; post-translational protein modification
Cellular component: mitochondrion
Genetic constraint (gnomAD): Loss-of-function variants: 31 observed, 14.28 expected, observed/expected ratio (o/e) 2.17. The synonymous counts are far from expectation, so gnomAD's model fits this gene poorly and the ratio says little. Missense variants: 447 observed, 272.39 expected, observed/expected ratio (o/e) 1.64, 90% interval 1.52 to 1.77. Synonymous variants: 254 observed, 136.21 expected, observed/expected ratio (o/e) 1.86, 90% interval 1.67 to 1.98.
Homologues: Orthologues: chimpanzee PDF (99% identical), macaque PDF (95% identical), dog PDF (79% identical), guinea pig PDF (79% identical), pig PDF (77% identical), mouse Pdf (73% identical), rat Pdf (72% identical), tropical clawed frog pdf (48% identical), zebrafish pdf (47% identical), Drosophila melanogaster CG31278 (35% identical), Drosophila melanogaster CG31373 (29% identical).
Diseases named in the same sentence as PDF in open-access papers:
PDF is named in the same sentence as 14 diseases in open-access papers, as found by Europe PMC text mining. Sharing a sentence is not in itself a finding about the gene and the disease. The quoted sentences say what the papers report.
bladder urothelial carcinoma (1 paper, 2020). "Until now, the roles of PDGFRA, OLR1, RAC3, PDF, OAS1, and SH3BP2 in bladder urothelial carcinoma remain largely unexplored." (PMID 32733809, 2020).
breast carcinoma (1 paper, 2013). "Stage-dependent expression of PDF was observed in the tissue samples where higher expression was found in early stages of colon and lung cancer, but later stages of breast cancer." (PMID 23815882, 2013).
chlamydial infection (1 paper, 2011). "This suggests that PDF inhibitors may be useful for prevention and treatment of chlamydial infection." (PMID 21719536, 2011).
colon cancer (1 paper, 2013). "Treatment of HT-29 colon cancer cells with the MEK inhibitor U0126 resulted in a 51% reduction in expression of PDF mRNA and a 47% reduction in MAP1D." (PMID 23815882, 2013). "To verify that the increased PDF mRNA levels translated to increased PDF protein levels, we screened two sets of colon cancer tissues for PDF expression." (PMID 23815882, 2013). "Protein levels of PDF were also determined in 2 colon cancer patients via western blotting." (PMID 23815882, 2013). "Further, PDF protein expression was elevated in colon cancer tissue samples." (PMID 23815882, 2013). "The over-expression of PDF and MAP1D, particularly in early-stage colon cancer, suggests that these enzymes are important for cancer cell growth." (PMID 23815882, 2013). "PDF mRNA levels were significantly increased in breast, colon, and lung cancer samples while MAP1D mRNA levels were increased in just colon cancers." (PMID 23815882, 2013). "MAP1D is over-expressed in colon cancer, but no study has reported the expression of PDF in cancerous compared to normal tissues." (PMID 23815882, 2013).
COVID-19 (1 paper, 2021). A disease caused by infection with severe acute respiratory syndrome coronavirus 2. "After comparing the collected genes, 460 host factors common to COVID-19 and dengue were found, including MMP2, PDF, PFKP, SLC25A3, IGF1, CCL4, TLR4, and AhR, and further analysis of interaction networks was performed." (PMID 34394108, 2021).
lung carcinoma (1 paper, 2013). "This is the first report showing that PDF is over-expressed in breast, colon, and lung cancers, and the first evidence that the MEK/ERK pathway plays a role in regulating the expression of PDF and MAP1D." (PMID 23815882, 2013). "Inhibition of the MEK/ERK, but not PI3K or mTOR, pathway reduced the expression of PDF and MAP1D in both colon and lung cancer cell lines." (PMID 23815882, 2013).
prostate carcinoma (1 paper, 2013). A carcinoma that arises from epithelial cells of the prostate gland. "PDF mRNA expression was significantly higher in the HT-29 colon, A549 lung, and PC-3 prostate cancer cell lines compared to the CCD-18Co colon, Hs888Lu lung, and PrEC prostate non-cancer cell lines." (PMID 23815882, 2013).
cancer (3 papers, 2013 to 2022). A tumor composed of atypical neoplastic, often pleomorphic cells that invade other tissues. "Human mitochondrial peptide deformylase (PDF) has been proposed as a novel cancer therapeutic target." (PMID 23815882, 2013). "The involvement of a growth-regulatory pathway in modulating PDF expression, provides further support that PDF promotes the growth of tumors and lends support to the pursuit of PDF inhibitors as cancer therapies." (PMID 23815882, 2013). "In conclusion, we found that PDF is up-regulated in several cancer types including breast, colon, and lung." (PMID 23815882, 2013). "The over-expression of PDF in several cancers and the inhibition of cancer cell growth by a PDF inhibitor suggest this enzyme may act as an oncogene to promote cancer cell proliferation." (PMID 23815882, 2013). "As a result, the goal of this research was to characterize the expression pattern of PDF and MAP1D in human cancer tissues in order to better understand their potential roles in these cancers." (PMID 23815882, 2013). "Recent studies also demonstrated that PDF also can be found in most eukaryotes, including parasites, plants, and mammals, but human PDF is overexpressed in cancer cells and not in normal cells." (PMID 27428963, 2016). "The expression of PDF and MAP1D varied with stage in these cancers." (PMID 23815882, 2013). "Therefore, the purpose of this study was to identify the expression profiles of PDF and MAP1D in human cancers compared to normal tissues and to identify a signaling pathway involved in regulating their expression." (PMID 23815882, 2013). "Given the role of human PDF and MAP1D in cancer cell growth and adhesion, we hypothesized that these proteins would be up-regulated in cancer cells and tissues compared to normal and their expression would be modulated by growth-regulatory pathways." (PMID 23815882, 2013). "PDF and MAP1D mRNA levels were elevated in cancer cell lines compared to non-cancer lines." (PMID 23815882, 2013). "TissueScanTM Cancer qPCR Arrays containing cDNA from 96 tissue samples representing eight different cancers (breast, colon, kidney, liver, lung, ovary, prostate, thyroid) were used to determine PDF expression in cancer compared to non-cancer tissues." (PMID 23815882, 2013). "We compared the expression of PDF and MAP1D in four different types (breast, colon, lung, and prostate) of cancer cell lines to non-cancer cell lines." (PMID 23815882, 2013).
infection (1 paper, 2021). The state of being infected such as from the introduction of a foreign agent such as serum, vaccine, antigenic substance or organism. "Likewise, the challenging of chilli plants with B. amyloliquefaciens CRN9 suppressed the infection of GBNV in chilli due to the induction of genes NPR1, PAL, PO, SAR8.2, PDF, LOX, EAS1, and WRKY33 associated with ISR/SAR pathway." (PMID 34946111, 2021).
PDF also shares sentences with these, for which no sentence is quoted: tumor (3 papers); bacterial infections (1); dengue (1); Fusarium infection (1); liver cancer (1).